PPARD (peroxisome proliferator activated receptor delta)
Diseases named in the same sentence as PPARD in open-access papers (continued):
Sharing a sentence is not in itself a finding about the gene and the disease.
colon carcinoma (continued). "Taken together, we conclude that PPARδ up-regulated the expression of NF-κB via activating its transcription activity in colonic cancer cells." (PMID 29416623, 2018). "As Cx43 is a downstream target of β-catenin, a key component of Wnt signaling pathway, nuclear accumulation of β-catenin turns on several genes including Cx43, COX-2, cyclin-D1, and PPARδ and contributes to the carcinogenesis of colon cancer." (PMID 21647307, 2011). "It was reported that PPARδ in colorectal cancer cells promotes cell proliferation and NSAIDs induce colon cancer cell apoptosis by suppressing PPARδ." (PMID 20862376, 2010). "Both prostanoids PGI2 and PGE2 havebeen known to activate PPARδ.The main role of PPARδ is in cell survival and this has been wellcharacterized in colon cancer." (PMID 19266055, 2009). "In cultured colon cancer cells, PPARδ inhibiteddifferentiation, conferred apoptotic resistance, and promoted cell migration, whereasprostacyclin, a metabolic product of COX-2 which modulates intestinaltumorigenesis, increased PPARδactivity." (PMID 18528523, 2008). "On the other hand, the following observations stronglysuggest that PPARδ enhances colon cancer formation." (PMID 18483618, 2008). "Dietary fish oil/pectin protected ratsagainst radiation-enhanced colon cancer by upregulating apoptosis in colonicmucosa, in part, by suppressing PPARδ." (PMID 18528523, 2008). "From a mechanisticstandpoint, PPARδ is activated in colon cancer cells by prostacyclin (PGI2) and inhibited by the NSAIDindomethacin, suggesting that its tumorpromoting action is related to inflammation, a condition that increases therisk of colon cancer." (PMID 18566686, 2008). "PPARδ was elevatedin colon cancer cells and was repressed by APC gene via the β-catenin/Tcf-4response elements in its promoter." (PMID 18483618, 2008). "Inhibition of COX2 by nimesulide attenuated colon cancer,and activation of PPARδ by GW0742 had inhibitory effects." (PMID 18528523, 2008). "PPARδ expressionwas elevated in colon cancer cells and was repressed by apc via the β-catenin/TCF-4 response elements in its promoter." (PMID 18528523, 2008). "By contrast, it has been reported that inactivation of the PPARδ gene results in reduced tumorigenicity and in vivo growth of HCT116 colon cancer cells and that a specific PPARδ agonist enhanced in vivo growth of intestinal adenoma of Apcmin mice." (PMID 16969348, 2006). "There is also cumulative evidence regarding the antiapoptotic effects of PPARδ in keratinocyte and colon cancer cells." (PMID 16969348, 2006). "We next investigated whether PPARδ could promote colon cancer cell proliferation and migration by activating NKD1 transcription." (PMID 40675969, 2025). "Studies have shown that PPARδ promotes the proliferation and migration of colon cancer cells." (PMID 40675969, 2025). "Additionally, scratch and Transwell assays indicated that the overexpression of PPARδ greatly increased the migration of colon cancer cells." (PMID 40675969, 2025). "PPARD is up-regulated in many cancers, including lung cancer, colon cancer, and breast cancer." (PMID 38212774, 2024). "Moreover, quantitative real-time PCR were performed to test the expression levels of HBXIP and PPARδ of the colonic carcinoma tissues from 148 colonic carcinoma paraffin-embedded specimen." (PMID 29416623, 2018). "Taken together, we conclude that the expression levels of HBXIP are positively associated with those of PPARδ in colonic carcinoma tissues, and the HBXIP/ PPARδ signaling may have important roles in the colonic tumorigenesis." (PMID 29416623, 2018). "The similar results were also confirmed in the HEK293T cells, suggesting that PPARδ could up-regulate the expression of NF-κB in the colonic cancer cells." (PMID 29416623, 2018). "One possible explanation is that the mechanisms by which PPARδ regulates NF-κB in inflammation might be different from that in colonic cancer." (PMID 29416623, 2018).
colon carcinoma (continued). "In our study, we investigate how HBXIP functions with PPARδ in promotion of colonic cancer cells." (PMID 29416623, 2018). "However, the knockdown of PPARδ abolished the HBXIP-induced proliferation, the similar results were also confirmed by colony formation assays, suggesting that HBXIP promoted the proliferation of colonic cancer cells through activating PPARδ." (PMID 29416623, 2018). "Therefore, we conclude that the oncoprotein HBXIP can up-regulate the expression of PPARδ in colonic cancer cells." (PMID 29416623, 2018). "It is reported that PPARδ in the cells indicates extreme malignancy in a colon cancer cell." (PMID 23316217, 2012). "The role of PPARδ in oncogenesis is controversial,especially in colon cancer." (PMID 18584037, 2008). "Functionally, the PPARδ/NKD1/MYC signaling pathway increased colon cancer cells’ proliferation, migration and angiogenesis capabilities in vitro and in vivo, suggesting that NKD1 could serve as a potential therapeutic target for colon cancer diagnosis and treatment." (PMID 40675969, 2025). "In addition to normal physiology, a role of PPARδ on colon cancer has been reported." (PMID 36162507, 2022). "Thus, we are interested in whether PPARδ is involved in HBXIP-enhanced proliferation of colonic cancer cells." (PMID 29416623, 2018). "Next, we wondered whether PPARδ could enhance the expression of NF-κB in colonic cancer cells." (PMID 29416623, 2018). "Thus, we first tested whether HBXIP is associated with PPARδ in colonic cancer cells, we found that HBXIP could up-regulate the expression of PPARδ in mRNA and protein levels in SW480 and HT-29 colonic cancer cells, respectively." (PMID 29416623, 2018). "Direct sequencing of the PPARD gene was performed in 303 primary tumors, in blood samples from 50 patients with ≥3 affected first-degree relatives, 50 patients with 2 affected first-degree relatives, 50 sporadic patients, 360 healthy controls, and in 6 colon cancer cell lines." (PMID 24391853, 2013). "Thus it is consideredpossible that PPARδ promotes the growth of colon cancers." (PMID 18584037, 2008). "However, the mechanism by which PPARδ promotes the progression of colon cancer remains unclear." (PMID 40675969, 2025). "We found that PPARδ is a transcription factor of the NKD1 gene, and our previous studies demonstrated that NKD1 promotes colon cancer cell proliferation and migration." (PMID 40675969, 2025). "LEF1 was also necessary for maximum expression of PPARδ and ACAD9 in the fully transformed DLD1 colon cancer cells." (PMID 31623618, 2019). "The expression of MYC, LEF1, PPARδ, and ACAD9 were closely correlated in a Western blot comparing colon cancer and normal adjacent benign tissue of human samples." (PMID 31623618, 2019). "Here we found that HBXIP increased the expression of PPARδ (peroxisome proliferator-activated receptor-δ) in gene and protein levels of SW480 or HT-29 colonic cancer cells." (PMID 29416623, 2018). "It has been reported that PGI2, the product of PTGIS, promotes colorectal cancer growth probably by activating PPARδ and inhibition of COX-2-derived PGI2 induces colon cancer cells apoptosis." (PMID 29892223, 2018). "The present study shows for the first time sequence analysis of the PPARD gene in diverse groups of CRC patients, healthy controls, and colon cancer cell line models." (PMID 24391853, 2013). "However, it is currently unclear whether PPARδ, like other downstream targets such as c-myc and cyclin D1, contributes to oncogenesis and the development of colon tumours." (PMID 16969348, 2006). "Despite strong evidence for PPARδ activation in the treatment of metabolic disorders, a major setback occurred after the PPARδ agonist GW501506 was found to promote carcinogenesis, particularly colon cancer, in rodent models." (PMID 34298687, 2021).
colon carcinoma (continued). "Using primary colon cancer cells, 3D tumor organoids and in vivo xenograft models, we showed that uptake of fatty acids promotes the expression of CPT1A through the activation of PPARδ." (PMID 32913185, 2020). "PPARδ also enhances the expression of VEGF, an angiogenic factor, in colonic carcinoma cells." (PMID 29416623, 2018). "Colon cancer presents an interesting model toexam the role of PPARδ in tumorigenesis since ApcMin mice exhibit constitutiveactivation of β-catenin/TCF signaling, the pathway believed toactivate PPARδ." (PMID 18566686, 2008). "The activation of Akt can trigger many downstream signaling cascades, and in colon cancer PGE2 has been shown to activate Akt and the downstream pathway of GSK-3β and β-catenin resulting in an increased proliferation, whereas an increased survival was due to Akt activation of PPARδ." (PMID 22276108, 2012). "Eventhough significant progress has been made, the mechanism by which NO-ASA exertsits chemopreventive effect against colon cancer is still not completelyunderstood.Our data indicate that NO-ASA could exert its colon chemopreventiveeffect, at least in part, by modulating PPARδ function." (PMID 18528523, 2008).
breast cancer (54 papers, 2008 to 2025). A primary or metastatic malignant neoplasm involving the breast. "Expression of the nuclear receptor peroxisome proliferator activated receptor delta (PPARδ) in breast cancer cells is negatively associated with patient survival, but the underlying mechanisms are not clear." (PMID 27270614, 2016). "PDK1 and PPARδ co-associate in DMBA-induced mammary tumors, and PPARδ activates PI3K/PDK1 signaling in a diverse range of cell types to enhance survival and growth." (PMID 21297860, 2011). "In addition, PPARδ upregulation in breast cancer cells is associated with more aggressive clinical behavior." (PMID 33808242, 2021). "Lastly, the co-association of PDK1 and PPARδ noted in mammary tumors may also have enhanced resistance of the receptor to ubiquitination and degradation." (PMID 21297860, 2011). "To explore the downstream signaling pathways regulated by the H3K18la/PPARD axis that contribute to breast cancer cell survival, we examined the KEGG database for components associated with the PPAR signaling pathway." (PMID 39922804, 2025). "Its mechanism is thought to be regulated by platelet-reactive protein-1 (TSP-1) and its degrading proteases, and activated PPARδ significantly inhibited breast cancer cell migration and TSP-1 expression." (PMID 37251321, 2023). "Through decreasing oxidative stress and increasing survival signaling responses, PPARD supports breast cancer cells to thrive under severe microenvironmental circumstances." (PMID 36476410, 2022). "Upregulation of PPARδ protected human breast cancer cells cultured in low-glucose conditions from oxidative stress, which was attributed to augmented antioxidant defense signaling mediated in part by catalase." (PMID 33808242, 2021). "Expression of PPARD in breast cancer cells increased cell migration in vitro and induced creation of lung metastases in vivo." (PMID 32947901, 2020). "The present findings show that activation of PPARδ regulates migration and invasion of human breast cancers MDA-MB-231, MDA-MB-435, and ZR-75-1 cells by upregulating ADAMTS1 expression, thereby modulating the level of TSP-1." (PMID 29212212, 2017). "In fact, different studies report that PPARδ can promote or inhibit tumorigenesis in MCF-7 human breast cancer cells." (PMID 29212212, 2017). "In this context, PPARγ activation by GW501516 increased arachidonic and linoleic acids in mammary tumors, and elicited an inflammatory gene signature in other animal models, which are also consistent with PPARδ-mediated repression of PPARγ." (PMID 28881566, 2017). "Conversely, disruption of PPARδ expression reduced tumorigenesis in experimental breast cancer models." (PMID 28881566, 2017). "Taken together, these results demonstrate that PPARδ suppresses migration and invasion of breast cancer cells by downregulating TSP-1 in a process mediated by upregulation of ADAMTS1." (PMID 29212212, 2017). "Although the role of PPARδ in the tumorigenicity of breast cancer is controversial, recent reports have shown the anti-proliferative activities of PPARδ in breast cancer cells." (PMID 29212212, 2017). "Although PPARδ is expressed by several tumor-derived cell lineages and primary human tumors, including liver, prostate, colon, gastric, and breast cancers, its exact role in cancer development is unclear." (PMID 29212212, 2017). "We show that activation of PPARδ by GW501516 inhibits migration and invasion of breast cancer cells, and that PPARδ exerts its inhibitory effects by downregulating TSP-1 expression in a process mediated by transcriptional upregulation of ADAMTS1." (PMID 29212212, 2017). "Here, we show that the GW501516-mediated activation of PPARδ suppresses migration and invasion of human breast cancers MDA-MB-231, MDA-MB-435, and ZR-75-1 cells." (PMID 29212212, 2017). "Here, we examined the association between TSP-1 and ADAMTS1 and the activity of ligand-activated PPARδ in terms of migration and invasion of human breast cancer cells." (PMID 29212212, 2017).
breast cancer (continued). "Although the role of PPARδ in tumorigenesis is highly controversial, the present data demonstrated that ligand-activated PPARδ suppresses migration and invasion of human breast cancer cells." (PMID 29212212, 2017). "We did also exclude that the mediator of ‘supraphysiological’ RA cancer-promoting action in breast cancer cells with inhibition of RARA transcriptional function is PPARD." (PMID 27894085, 2016). "The results in this manuscript indicate that PPARD is expressed by breast cancer cells with more aggressive clinical behavior." (PMID 27270614, 2016). "There was a trend toward higher expression of PPARD in lines derived from basilar breast cancers, which are considered to have more aggressive clinical behavior." (PMID 27270614, 2016). "Transgenic expression of PPARδ increased the ability of human breast cancer cell lines to migrate in vitro and form lung metastases in mice." (PMID 27270614, 2016). "As shown here by both genetic and pharmacological approaches, we discounted a role of PPARD in the T47D breast cancer cell context with maximal inhibition of RARA transcriptional function." (PMID 27894085, 2016). "Upregulation of PPARδ by glucocorticoids or synthetic agonists also protected human breast cancer cells from low glucose." (PMID 27270614, 2016). "PPARδ activation can stimulate the expression of VEGFA in breast cancer and prostate cancer." (PMID 34712608, 2021). "In mice, expression of PPARδ is related to prognosis and metastatic ability of breast cancer cells." (PMID 32198386, 2020). "Furthermore, increasing the expression of PPARδ through a transgenic method enhances the migratory ability of cells in human breast cancer lines." (PMID 31336903, 2019). "In addition, pretreatment with GSK0660 significantly inhibited GW501516-induced expression of ADAMTS1 mRNA, confirming involvement of PPARδ in GW501516-mediated upregulation of ADAMTS1 in breast cancer cells." (PMID 29212212, 2017). "Furthermore, ligand-activated PPARδ suppressed invasion of breast cancer cells in an ADAMTS1-dependent manner." (PMID 29212212, 2017). "Furthermore, GW501516-activated PPARδ suppressed invasion of human breast cancer cells via a mechanism mediated by ADAMTS1." (PMID 29212212, 2017). "However, the present data clearly demonstrate that GW501516-activated PPARδ suppresses migration and invasion of human breast cancers MDA-MB-231, MDA-MB-435, and ZR-75-1 cells." (PMID 29212212, 2017). "In addition to PPARδ-mediated tumor progression, PPARδ ligand GW0742 reduces colon or breast cancer event, this event is reversed in PPARδ−/− mice." (PMID 28948004, 2017). "Among the three PPAR isotypes, PPARδ is distinguished by its ability to function as a promoter of tumorigenesis in many instances, and is highly expressed in colon cancer, head and neck cancer, endometrial cancer and breast cancer." (PMID 21297860, 2011). "Thus, we hypothesized that ligand-activated PPARδ plays a central role in the tumorigenicity of human breast cancers, by modulating the expression of TSP-1 through its degrading protease ADAMTS1." (PMID 29212212, 2017). "Drugs that target PPARδ may have a role in the treatment of breast cancer." (PMID 27270614, 2016). "GW501516-activated PPARδ significantly downregulates TSP-1 expression by MDA-MB-231, MDA-MB-435, and ZR-75-1 human breast cancer cells." (PMID 29212212, 2017). "PPARδ-induced upregulation of ADAMTS1 is a key event during PPARδ-dependent suppression in the migration and invasion of human breast cancers MDA-MB-231, MDA-MB-435, and ZR-75-1 cells." (PMID 29212212, 2017). "Activation of PPARδ by GW501516, a specific ligand for PPARδ, led to marked inhibition in the cell migration and TSP-1 expression of breast cancer." (PMID 29212212, 2017).
breast cancer (continued). "In addition to activation of the prostaglandin axis, PPARδ increases expression of the acute phase proteins Saa1, Saa2, S100a8, and S100a9, as well as several members of the kallikrein gene family, all of which are elevated in ER+ breast cancer and whose promoter regions contain PPREs." (PMID 28077942, 2016). "Of these, peroxisome proliferator-activated receptor delta (PPARD) protein showed increased expression in breast cancer with negative impact on relapse free survival." (PMID 32947901, 2020). "Consistent with our previous study demonstrating involvement of PPARδ in negative regulation of melanoma cell migration and invasion, we found here that PPARδ-mediated downregulation of TSP-1 is likely responsible for inhibition of aggressive breast cancer." (PMID 29212212, 2017). "Interestingly, tumorigenesis in both AIB1 and PPARδ mice was dependent on mTOR activation downstream of phospholipid catabolism and an inflammatory phenotype, which may suggest a possible link between lipid biosynthesis, ER+ breast cancer and obesity, particularly in postmenopausal women." (PMID 28881566, 2017). "TSP-1 is reported to induce an invasive phenotype in various cancer cells, we asked whether GW501516-activated PPARδ induces phenotypic changes, such as invasion, via ADAMTS-1-mediated regulation of TSP-1 in breast cancer cells." (PMID 29212212, 2017). "Although there are numerous studies of these pathways in immune tolerance, the role of PPARδ in this process has not been examined in mammary tumor models." (PMID 28077942, 2016). "PPARA, PPARD, and PPARG were involved in many of the indirect effects identified in breast cancer." (PMID 18358079, 2008). "Similarly, animals treated with the PPARδ agonist GW501516 exhibited an accelerated formation of breast cancer tumors, particularly adenosquamous and squamous cell carcinomas, and tumors of mice treated with GW501516 exhibited increased levels of PPARδ and activated PDK1." (PMID 37251321, 2023). "Thus, the majority of aggressive breast cancers would be expected to be responsive to a PPARδ agonist or PPARγ antagonist that could reverse the negative regulation by PPARγ on the ER+ lineage." (PMID 28881566, 2017).